RAD51 (RAD51 recombinase)
Diseases named in the same sentence as RAD51 in open-access papers (continued):
Sharing a sentence is not in itself a finding about the gene and the disease.
Fanconi anemia (continued). "Recent work has indicated that mediators, RAD51, and the Fanconi anemia complex have functions in replication fork stabilization that are independent of their roles in DSB repair." (PMID 24027577, 2013). "Fanconi anemia (FA) is a largely autosomal recessive inherited bone marrow failure syndrome, except for FA complementation group B (FANCB), which is X-linked recessive, and FANCR/RAD51, which exhibits autosomal dominant cellular effects." (PMID 40970532, 2025). "HDR with dsDNA templates uses the RAD51-dependent HR pathway discussed in Chapter 2, while HDR with ssDNA is RAD51-independent and involves proteins from the Fanconi Anemia pathway through an unknown mechanism." (PMID 39996750, 2025). "It has been reported that the MCM8/9 complex participates in interstrand crosslink repair by functioning in RAD51-dependent HR repair downstream of the Fanconi anemia (FA) pathway, and Mcm8 and Mcm9 KO mice share the similar phenotype with FA-null mice of massive loss of proliferating PGCs." (PMID 38858601, 2024). "This phenotype could be explained by reduced expression of several genes of the Fanconi anemia DNA repair pathway, including Fancd2, Fanci and Rad51, the promoters of which contain functionally relevant bipartite DBSs." (PMID 37661832, 2023). "However, RB1 (25%), as well as genes involved in the HRR (e.g., RAD51 in 18.8%) and Fanconi anemia (e.g., BRCA2 in 12.5%) pathways, were also recurrently hit by HetDels." (PMID 35406559, 2022). "The BRCAness phenotype may be induced pharmacologically or due to genetic alterations in HR genes other than BRCA1/2, including ATM, ATR, CHEK1, RAD51, the Fanconi anaemia complementation group family of genes and others." (PMID 36010882, 2022). "Additional evidence for this non-recombinogenic role of Rad51 in protecting stalled forks came from the analysis of a rad51-T131P mutation in a patient with Fanconi anemia." (PMID 34680945, 2021). "As well, two RAD51 paralogs have been reported to be Fanconi anemia proteins." (PMID 31584931, 2019). "Indeed, regulation of Rad51, essential for homologous recombination as well as breast cancer 1 (Brca1) and Fanconi anemia, complementation group A (Fanca) that build DNA repair complexes were found to be repressed." (PMID 21152443, 2010). "In addition, a recent study in Fanconi anemia cells showed that SLFN11 hinders the binding of the single-strand binding recombination protein RAD51 at stalled forks and destabilizes nascent DNA tracts, leading to degradation of the stalled forks by the nucleases MRE11 and DNA231." (PMID 35768579, 2022). "This pathway involves multiple proteins, including BRCA1, BRCA2, proteins of the MRN complex, CtIP, RAD51, ATM, H2AX, PALB2, RPA, RAD52, and proteins of the Fanconi anemia pathway." (PMID 38236558, 2024). "In our experiments, the most significant upregulated genes included FANCD2, a player in Fanconi anemia (FA), and several genes playing a role in the HR-mediated repair of double-strand breaks (DSBs) such as BARD1, BRCA2, RAD51 and DNA2." (PMID 36672885, 2023). "Two genes in the HRR pathway, RAD51, and XRCC2, cell cycle regulation (CHEK2), and Fanconi Anemia (UBE2T) were significantly upregulated in Groups 3 and 4 (p = 0.042, p = 0.0042, p = 0.021, and p = 0.023, respectively)." (PMID 37334114, 2023). "HRR alterations involve Fanconi anemia genes (PALB2, FANCA, FANCL, FANCI, FANCC), core RAD genes (RAD50, RAD51, RAD51B, RAD51C) as well as DNA damage response genes (ATM, ATR, CHEK1, CHEK2)." (PMID 36531003, 2022). "The components of the Fanconi anemia (FA) and HR pathways include RAD51 (FANCR), FANCD2, BRCA1 (FANCS) and (FANCD1), and these pathways were shown to coordinately suppress nascent DNA degradation." (PMID 34144707, 2021).
Fanconi anemia (continued). "Fanconi anemia genes such as BRCA2/FANCD1, RAD51C and RAD51, homologous to the bacterial RecA, are involved in repair of DNA DSBs by homologous recombination." (PMID 33987182, 2021). "MCM8-9 dimer also works downstream of the Fanconi anemia and the BRCA2/Rad51 pathways and is required for HR that promotes sister chromatid exchanges, as a hexameric ATPase/helicase." (PMID 32841224, 2020). "The associations involving DNA double-strand break repair pathway and Fanconi anemia, in particular, were also evident when examining key individual genes, including BRCA1, BRCA2, FANCD2, FANCI, and RAD51." (PMID 31610796, 2019). "Consistent with both GSEA and the Metascape pathway analyses, we validated downregulation of genes involved in the Fanconi anemia pathway, such as BRCA2 and RAD51, after TIGAR KD with two different shRNAs." (PMID 31508509, 2019). "This protection of forks from degradation required Rad51 filament formation plus filament stabilization by BRCA2 and the core Fanconi anaemia pathway." (PMID 30220600, 2018). "Fanconi anemia (FA) is a rare (1:160,000), principally autosomal recessive hereditary disease (except for FANCB and FANCR/RAD51); it develops due to biallelic germline downregulation of any one of the 22 currently identified FANC complementation genes (FANCA–FANCW)." (PMID 39519169, 2024). "Mechanistically, we find that multiple genes in the homologous recombination and Fanconi anemia repair pathways, including BRCA1, FANCD2, and RAD51, are dependent on Wnt/β‐catenin signaling in Wnt‐high cancers, and treatment with a PORCN inhibitor creates a BRCA‐like state." (PMID 33660437, 2021). "This process is genetically independent of the Rad51-dependent homologous recombination and Fanconi anemia pathways, is strongly antagonized by non-homologous end-joining, and is mediated almost entirely by the alternative end-joining enzyme polymerase θ." (PMID 34799578, 2021). "Other defects in homologous recombination repair genes, such as EMSY, RAD51, ATM, ATR, Fanconi anemia, BARD1, BRIP1, PALB2, RB1, NF1, CDKN2A, and the suppression of BRCA1 transcriptional activation through gene methylation, are associated with homologous recombination deficiency (HRD)." (PMID 32679669, 2020). "Additionally, Su-Dhl-4 cells treated with entinostat or tazemetostat also showed downregulation of RAD51, RAD54L, BRCA2, and three Fanconi anemia genes (FANCA, FANCB, and FANCM)." (PMID 31829282, 2019). "Besides, some other core components of HR such as RAD51 recombinase (RAD51), ATM serine/threonine kinase (ATM), ATR serine/threonine kinase (ATR), partner and localizer of BRCA2 (PALB2), and Fanconi anemia gene family are determinants of intact HR as well." (PMID 31737426, 2019). "Fanconi anemia (FA) is a recessive disorder caused by biallelic mutations in one of the (so far) nineteen FANC genes, of which only two (RAD51 and UBE2T) are not covered by the TruSight Cancer panel." (PMID 29659569, 2018). "Gene Set Enrichment Analysis (GSEA) revealed significant enrichment of Fanconi anemia pathway genes in the radiosensitive group in comparison with the radioresistant group, and, interestingly, no RAD51 enrichment was pointed out." (PMID 30282933, 2018). "However, with 12 h of bortezomib treatment, we did not observe a reduction in Fanconi anaemia (FA) complementation group D2 (FANCD2) or RAD51, two factors that were depleted in multiple myeloid cells upon similar treatment." (PMID 37607592, 2023). "When complementary ssODN are used as DNA donors, DSBs are processed by a distinct mechanism, the single-strand template repair (SSTR) pathway, which is independent of RAD51 but requires an operative Fanconi anemia (FA) pathway and at least two RAD51 paralogs (RAD51C and XRCC3)." (PMID 33535527, 2021).
Fanconi anemia (continued). "This unexpected outcome may result from either the large number of pairing disrupting mutations in the protospacer region and/or the observation that ssDNA repair templates may use the Fanconi Anemia-dependent but not the Rad51-dependent pathway." (PMID 30504134, 2019). "Some of these non-core genes include ARID1A, ATM, RAD51, CHEK2, and the Fanconi anemia genes." (PMID 39860372, 2025). "Additionally, most chemicals also inhibited IR-induced RAD51 foci formation and DNA double-strand break repair by HR, but generally not BRCA1 foci formation, indicating that they inhibit multiple discrete steps of the DNA damage response and are not specific inhibitors of the Fanconi anemia pathway." (PMID 22537224, 2012).
prostate carcinoma (75 papers, 2004 to 2026). A carcinoma that arises from epithelial cells of the prostate gland. "In osteosarcoma and prostate carcinoma cell lines, RAD51 knockdown was associated with an increase in radiosensitivity." (PMID 38001574, 2023). "In our previous study we found a significant relationship between RAD51 polymorphism rsl801320 and an increased risk of prostate cancer." (PMID 31186630, 2019). "Knockdown of SMYD3 caused differentially expressed DNA repair genes RAD50 and RAD51 in prostate cancer cells." (PMID 28630472, 2017). "A significant relationship was detected between the RAD51 gene rs1801320 polymorphism and increased prostate cancer risk." (PMID 26339569, 2015). "The results of the present study show that the RAD51 gene rs1801320 polymorphism doubles the risk of prostate cancer in the studied population." (PMID 26339569, 2015). "The cohort of modulated genes did not contain any cell cycle-associated genes, DNA-binding genes (e.g. RAD51) or transcriptional activation genes (e.g. Id-1) we have already reported in aggressive primary prostate cancers." (PMID 21799931, 2011). "As we have previously shown the rs1801320 polymorphism in RAD51 may contribute to prostate cancer susceptibility in Poland." (PMID 31186630, 2019). "Our results indicate that the RAD51 gene rs1801320 polymorphism may contribute to prostate cancer susceptibility in Poland." (PMID 26339569, 2015). "While BRCA1, FANCG and RAD51 have previously been linked to various treatment responses in a number of cancers limited research exists investigating the association between RT-induced regulation of these genes in radiation resistant prostate cancer." (PMID 25369795, 2014). "Hence, the RAD51 gene rs1801320 polymorphism may act as an independent biomarker of prostate cancer risk in Polish population." (PMID 26339569, 2015). "The findings suggest that RAD51 may be considered as a prostate cancer susceptibility gene." (PMID 26433958, 2015). "Saruparib is a first-in-class PARP1 inhibitor with exquisite PARP1 selectivity that is being tested in the phase 1/2a PETRA trial in pretreated solid tumors, including prostate cancer, with a BRCA, RAD51, or ATM mutation." (PMID 39882554, 2025). "Next, SNVs in DNA repair genes (RAD51-associated protein 1 [RAD51 AP1], structural maintenance of chromosomes 1A [SMC1A], and activating signal cointegrator 1 complex subunit 3 [ASCC3]) were observed only in the RR prostate cancer cells." (PMID 39719436, 2024). "The effect of RAD51 knockdown on prostate cancer (PCa) cell lines was demonstrated using Cell Counting Kit-8, clone formation, and transwell migration experiments." (PMID 37251536, 2023). "BRCA2 mutations are known to be associated with a higher prostate cancer mortality, likely due to the direct involvement of BRCA2 in the homologous recombination process, as it mediates the recruitment of RAD51 to DNA double-strand breaks." (PMID 35740343, 2022). "In prostate cancer cells the expression of the DNA repair protein RAD51 was reduced by GZ17-6.02 after 6h of exposure and that DNA damage measured via comet assays persisted for up to at least 6h." (PMID 36408163, 2022). "Our study showed that rs5030789 polymorphism in RAD51 and rs1799796 in XRCC3 are associated with the occurrence of prostate cancer in Polish men." (PMID 31186630, 2019). "Our findings indicate the importance of RAD51 and XRCC3 polymorphisms in the development of prostate cancer." (PMID 31186630, 2019). "The presence of the GG genotype in both polymorphic sites of RAD51 and XRCC3 increases the risk of prostate cancer (OR = 2.782, p = 0.038 for rs5030789; OR = 1.986, p = 0.041 for rs1799796)." (PMID 31186630, 2019). "A recent study showed that Stat5 induces Rad51, a key protein controlling DNA repair process, in prostate cancer cells; treatment cells with a Stat5 inhibitor sensitizes prostate cancer cells to radiation." (PMID 31366128, 2019).
prostate carcinoma (continued). "Conversely, inhibition of STAT5a/b depletes RAD51 levels, disrupting HR DNA repair, and sensitizing prostate cancer to radiation." (PMID 31993371, 2019). "A significant association was detected between RAD51 rs5030789 polymorphism and XRCC3 rs1799796 polymorphism and an increased risk of prostate cancer." (PMID 31186630, 2019). "Because the polymorphism rs5030789 in RAD51 and polymorphism rs1799796 in XRCC3 increase the risk of prostate cancer, the correlation of these polymorphisms with age and clinicopathological characteristcs of prostate cancer patients was examined." (PMID 31186630, 2019). "The aim of our study was to investigate single nucleotide polymorphisms (SNPs) in RAD51 (rs2619679, rs2928140, and rs5030789) and XRCC3 (rs1799796) involved in DNA double-strand break repair and their relationship to prostate cancer." (PMID 31186630, 2019). "The odds ratio (OR) analysis showed that rs5030789 polymorphism in RAD51 and rs1799796 polymorphism in XRCC3 are associated with susceptibility to prostate cancer." (PMID 31186630, 2019). "On the other hand, it has been demonstrated that PI3K/Akt/mTOR inhibitors enhance radiosensitivity of radioresistant prostate cancer cells in part by downregulating proteins involved in HR (such as Rad51) and NHEJ (such as Ku70/Ku80)." (PMID 31780937, 2019). "For example, active phospho-ATM is co-localised with the hypoxic marker CAIX in tumour xenografts and RAD51 down-regulation was observed in cervical and prostate cancer xenografts as well as in a glioma model." (PMID 30943920, 2019). "Statistically significant differences were found in the distribution of genotypes and alleles for rs5030789 and rs1799796 polymorphism in RAD51 and XRCC3, respectively, between control group and prostate cancer patients." (PMID 31186630, 2019). "The association between the presence of polymorphisms rs1801320 and rs1801321 of RAD51, rs10483813 and rs3784099 of RAD51B, rs3218536 of XRCC2, and rs861539 of XRCC3 and the risk of prostate cancer was examined." (PMID 26339569, 2015). "Although the contribution of the homologous recombination mediators BRCA1 and BRCA2 to prostate cancer has been previously investigated, this is the first study to address the importance of RAD51 genetics in the occurrence of sporadic prostate cancer." (PMID 26433958, 2015). "The high frequency of allelic losses at the RAD51 locus indicates the important role played by this gene in prostate cancer and sheds light on the novel perspective of genetic changes associated with its development." (PMID 26433958, 2015). "Consistent with the drug resistance of the cancer cells conferred by the overexpression of RAD51, down-regulation of RAD51 also increased the radio-sensitivity of prostate cancer cells and malignant glioma cells." (PMID 25539919, 2015). "RAD51 has previously been proposed as a possible target for radiosensitisation through inhibition using imatinib in prostate cancer xenografts." (PMID 25369795, 2014). "Three human prostate cancer cell lines have exhibited increased radiosensitivity together with significant downregulation of Rad51, as compared to control cells." (PMID 15150571, 2004). "Upregulation of RAD51 indicates poor prognosis in breast, ovarian, and prostate cancers." (PMID 40847617, 2025). "Furthermore, mutations in DNA damage repair genes such as BRCA2, ATM, CHEK2, BRCA1, RAD51, and PALB2 have been implicated in familial prostate cancer." (PMID 40716035, 2025). "In prostate cancer cell line models CHD1 deletion did not induce HR deficiency as detected by RAD51 foci formation assay or mutational signatures, which was consistent with the moderate increase of olaparib sensitivity." (PMID 38645014, 2024). "Moreover, longer exposure to hypoxia (>24 h) progressively decreased the expression of RAD51, required for homologous recombination (HR) during double strand break repair, in prostate cancer." (PMID 37020039, 2023).